CD4 (CD4 molecule)
Diseases named in the same sentence as CD4 in open-access papers (continued):
Sharing a sentence is not in itself a finding about the gene and the disease.
glioma (continued). "Cryoablated tumors in glioma mouse models induced an antitumor cellular immunological response, which increased the percentage of CD3+ T and CD4+ T cells in blood as was the case for NK cells." (PMID 31289616, 2019). "Previous studies have demonstrated that tumor infiltrating lymphocytes(TILs), especially the CD4+ T cells and CD8+ T cells, are correlated with clinical prognosis in gliomas." (PMID 31885736, 2019). "In glioma patients, the accumulation of CD4+/CD8+ T cells and T regulatory cells (Tregs) that express high levels of CTLA-4 and PD-1, or the high expression of PD-L1 in glioma cells correlates with WHO high grade and short survival." (PMID 30857299, 2019). "Elevated numbers of perivascular CD4+ TILs strongly correlated with CD34+ tumor vascularity in both primary and recurrent glioma." (PMID 32914058, 2018). "Since this work, there has been an increased focus on the contributions of CD4+ Th cells and subset CD4+FOXP3+ Tregs to glioma progression at both the pre-clinical and clinical levels." (PMID 32914058, 2018). "The anti-tumorigenic potential of alternate lymphocytic populations is also supported by a study, which expanded and differentiated glioma patient T cells (of mixed CD3+CD4−CD8−, CD4+, and CD8+ subsets) ex vivo using IL-2, IL-15, and IL-21." (PMID 32914058, 2018). "In glioma patients, the expression of TIM-3 on CD4+T cells and CD8+T cells is significantly elevated than in healthy controls, and the higher expression level of TIM-3 on T cells is associated with tumors of higher grades." (PMID 27756892, 2017). "This intratumoral infiltration with CD4+ and CD8+ T cells was also seen in preclinical glioblastoma (GL26 glioma-bearing C57BL/6 mice) after immunomodulatory treatment." (PMID 28524099, 2017). "A study in glioma patients showed that CTLA-4 is highly expressed on T cells, specifically the effector CD4+T cells and Tregs." (PMID 27756892, 2017). "The proportion of PD-1+ cells among peripheral blood CD4+ and CD8+ T cells in glioma patients is higher than that in healthy controls." (PMID 27756892, 2017). "Upon recurrence in primary gliomas, similar kinetic changes were found between tumor blood vessels and each TIL subset in all groups, but only CD4+ including Foxp3+ TILs, positively correlated with the density of tumor blood vessels." (PMID 29163521, 2017). "We next exposed CD4+ CD25− T cells to SEB and glioma cell extracts in the culture in the presence of DCs for 6 days." (PMID 28002799, 2017). "Together with glioma extracts (the specific Ag), SEB facilitates the generation of glioma specific CD4+ IL-9+ T cells." (PMID 28002799, 2017). "In an experimental glioma model, anti-CTLA-4 mAb procured an 80% long-term survival rate, concurrent with enhanced proliferation of CD4+ CD25− T cells and resistance to suppression by Treg cells." (PMID 26217588, 2015). "The observation of increased CNS-infiltrating CD8+ and CD4+ T cells, macrophages, and myeloid derived suppressor cells in mice bearing GL261 and GL261-Quad gliomas sets the stage for studies aimed at defining the relationships between these cell types." (PMID 25933216, 2015). "Fittingly described as a soluble “humoral immunosuppressive” factor, glioma-derived TGF-β significantly depressed lymphocyte functions and induced systemic lymphopenia, particularly in CD4+ T helper cell populations." (PMID 26217588, 2015). "In one report, cyclooxygenase-2 (COX-2) overexpressing glioma via Prostaglandin E2 (PGE2) synthesis induced mature DCs to express high levels of IL-10, which in turn induced CD4+ T cells that secreted copious amounts of IL-10 and TGF-β." (PMID 23874336, 2013). "The six enriched gene sets included gene signatures associated with microglia/macrophages, M1 and M2 macrophages and glioma infiltrating microglia/macrophages (GIM), along with the monocyte, granulocyte and naïve CD4 T cell gene sets." (PMID 22937035, 2012).
glioma (continued). "The average CD4+IL-17+ cell frequency is 12±3.7%, 12±1.1%, 0% and 10±1.5% in PBS-dLN, glioma-dLN, PBS-brain and glioma-brain, respectively." (PMID 21060663, 2010). "This clone demonstrated robust viral propagation and profound syncytium formation in CD4+, CXCR4-expressing human glioma NP-2 cells, indicating that p05MYKL045.1 is a CXCR4-using virus." (PMID 19688091, 2009). "The FACS analysis revealed an increase in the percentage of CD4+ (2.99 ± 0.15) and CD8+ (1.82 ± 0.13) T cells in the bone marrow of glioma-bearing mice when compared to untreated glioma-free mice (controls)." (PMID 20339520, 2009). "Using an S100a4-GFP knock-in reporter mouse with syngeneic mouse glioma models, we previously showed that GFP+ glioma infiltrating CD4 T cells from S100a4 -/- mice had reduced ability to inhibit T cell proliferation in vitro compared with their counterparts from S100a4 GFP/+ mice." (PMID 40078995, 2025). "We show that FH is expressed in glioma and that high levels correlate with a worse prognosis and a higher occurrence of Tregs but not nonregulatory CD4+ T cells." (PMID 39378431, 2025). "Our previous findings revealed upregulated levels of CD4 + TILs and downregulated levels of CD8+ TILs in high-grade gliomas compared to low-grade gliomas, which are independently associated with shorter progression-free survival (PFS) and overall survival (OS) in GBM." (PMID 40097979, 2025). "In addition, the expression of CMTM3 was positively correlated with macrophages, dendritic cells, and CD4 + T cells in grade II and III gliomas." (PMID 40179060, 2025). "Meanwhile, Kim and colleagues observed that mice bearing the mouse glioma cell line GL261 had a higher percentage of TIM-3 positivity on brain-infiltrating CD4+ and CD8+ T cells compared to non-tumor–bearing control mice." (PMID 40072074, 2025). "They showed that CD4+ and CD8+ T cells from high-grade glioma patients (grade III n = 9; grade IV n = 7) displayed significantly higher percentage of TIM-3 positivity than CD4+ and CD8+ T cells from low-grade glioma patients (grade I n = 5; grade II n = 9)." (PMID 40072074, 2025). "Furthermore, the TIMER database revealed a correlation between tumour purity and immune cell infiltration (including B cell, CD8+ T cell, CD4+ T cell, macrophage, neutrophil, dendritic cell) in GBM and low‐grade glioma, with five disulfidptosis genes involved." (PMID 39993959, 2025). "Observations in glioma animal models indicated that the expression of G9a can enhance the influx of IFN‐γ+CD4+ and CD8+ T cells, while simultaneously diminishing the entrance of PD‐1+CD4+ T cells, MDSCs and M2 macrophages within the TME." (PMID 40665579, 2025). "The Step 4 analysis of immune cell proportions infiltrating in cancer revealed that SASP activation was positively correlated with the infiltration of macrophages and T cell helper cells, but negatively correlated with the recruitment of CD4 + T cells and CD8 + T cells in IDH wt glioma." (PMID 40781221, 2025). "Furthermore, GITR expression on intratumoral CD4+ T cells was highest in mice receiving GITRL-Fc, suggesting a feedback loop in the GITR expression/pathway activation in syngeneic gliomas." (PMID 40580238, 2025). "These bone marrow-derived CCR2+/CX3CR1+ cells also co-express markers that correspond to M-MDSCs, namely, CD45+, CD11b+, Ly6Chi, and Ly6G−, migrate to glioma-secreted CCL2 and CCL7, and suppress the proliferation and IFN-γ secretion of both CD4+ and CD8+ T cells." (PMID 39272914, 2024). "CD4+ TILs subset was more enriched in meningiomas (log median 6.37, IQR [5.62, 7.25]) than in glial tumours (p < 0.001), whereas the expression in gliomas was significantly higher in GBMs (log median 5.62, IQR [4.67, 6.30]) than in astrocytomas (log median 4.50, IQR [2.50, 5.60]) (p = 0.0026)." (PMID 38816839, 2024).
glioma (continued). "Flow cytometric evaluations of CD8+, CD4+, and CD11b+ cells isolated from these organs revealed that CD8+, CD4+, and CD11b+ populations in the intracerebral glioma tissue were significantly more hypoxic than those in subcutaneous tumors regardless of CAR-T cell administration." (PMID 38386420, 2024). "In this context, previous research showed an increased CD4+ and CD8+ T cell and natural killer (NK) cell infiltration in the TME of lower grade gliomas (LGGs), and conversely a sparse infiltration in immunosuppressed high-grade gliomas (HGGs)." (PMID 38816839, 2024). "CLIC4 expression levels were positively correlated with specific markers of macrophages (CD80, CD86, MRC1), neutrophils (FCGR3A, FCGR3B), eosinophils (SIGLEC8, IL3RA), T cells (CD3D, CD4), CD8+ T cells (CD8A, CD8D), NK cells (NCAM1), and B cells (CD19) in glioma." (PMID 39595145, 2024). "Moreover, the higher enrichment of resting memory CD4 + T cells in the CRG and immune high-risk subgroups implies that their activation, proliferation, and differentiation into specific Th subsets may offer new insights into the pathogenesis and therapy for gliomas." (PMID 38956740, 2024). "mRNA levels of CCL2 were not significantly different when glioma cells were co-cultured with CD4 + helper T cells." (PMID 39046599, 2024). "CCL2 mRNA was expressed in all glioma cell lines, and expression increased when exposed to Tregs but not CD4 + helper T-cells." (PMID 39046599, 2024). "The results demonstrated that HK3 could induce higher infiltration level of M2 macrophages, neutrophils, and various subtypes of activated memory CD4+ T cells into the TME and could be a predictor of the unfavorable prognosis of glioma in vitro and in vivo." (PMID 37779195, 2023). "Similarly, our results showed that TCL+TIO3 obviously increased the percentage of CD4+ and CD8+ T cells in the lymphocytes of glioma-bearing mice compared with the TCL and PBS groups (p <0.001)." (PMID 36776837, 2023). "It is assumed that a reduced membrane Hsp70 density on grade 4 versus grade 3 primary glioma cells and reduced CD3+/CD4+ T cell counts in GBM might drive an immunosuppressive tumor microenvironment." (PMID 38137456, 2023). "On the other hand, there is a negative correlation between survival outcomes in glioma patients and high degrees of eosinophils, mast cell activation, Monocytes, NK cell activation and T cell CD4 memory quiescence." (PMID 37934582, 2023). "In addition to the activation of antitumor effector cells, TIO3 also reduced the expression of PD1 on CD4+ T cells, CD8+ T cells and NK cells and inhibited PD-L1 expression in glioma tissues and tumor-infiltrating neutrophils." (PMID 36776837, 2023). "Because B cells and CD4+ T cells usually inhibit tumor growth while CAFs and macrophages promote tumor growth, it was concluded that high levels of GSDMD induced an immunosuppressive microenvironment and promoted glioma progression." (PMID 37371484, 2023). "Moreover, previous preclinical studies demonstrated that silencing glioma tumor cells-derived Gal-1 significantly decreased the number of brain-infiltrating macrophages, Tregs, and MDSC while increasing CD4+ and CD8+ T cells." (PMID 36980184, 2023). "Glioma stem cell (GSC)‐derived exosomes function as mediators of intercellular communication and promote tumor immune escape by inhibiting T cell activation, proliferation, and Th1 cytokine production while enhancing the proliferation of purified CD4+ T cells." (PMID 37170647, 2023). "Our results showed that DDOST expression was inversely correlated with CD4+ T cells and further illustrated that DDOST may contribute to the immunosuppressive microenvironment of gliomas, which affected the effective of immunotherapy drugs." (PMID 35812432, 2022). "Furthermore, we found a significant increase of CD3, CD4, CD8, CD16, CD11, CD22 positive immune cell infiltrates in grade IV glioma tissues compared with grade II and III." (PMID 35493457, 2022).
glioma (continued). "High-grade gliomas had stronger EDEM2 expression based on immunohistochemistry, and the expression of cluster of differentiation 68 (CD68), cluster of differentiation 4 (CD4), and cluster of differentiation 8 (CD8) was higher in the samples." (PMID 36727065, 2022). "Interestingly, IDH-wildtype glioma is usually associated with more lymphocyte infiltration and PD-L1 expression while IDH-mutant gliomas have less IFN-γ and lower infiltration of CD8+ and CD4+ T cells." (PMID 35203421, 2022). "Similarly, the genes with increased copy numbers, such as CD4, PIK3CA, and P2RX7, had higher expression levels in glioma, indicating a positive correlation of CNVs with the expression levels of ICD-related genes." (PMID 36428756, 2022). "Compared to those who did not use DEX, glioma patients who used DEX were also more likely to have a CD4 count < 200, CD4 count < 500, ANC ≥ 8870, ALC < 1000, total cell count ≥ 10,000 and an NLR ≥ 4 (all p < 0.001)." (PMID 35716311, 2022). "Furthermore, in the performed co-expression of COL6A2 with the immune gene CD4, it was shown that COL6A2 and CD4 were well co-expressed in glioma tissues at different concentrations." (PMID 36505882, 2022). "It is interesting to note that, as in glioma, LGG showed a clear positive correlation between PSAT1 expression and infiltration of B cells, CD8+ T cells and neutrophils, but a negatively correlation with infiltration of CD4+ T cells." (PMID 36105075, 2022). "On the other hand, CD8+ population was found in the majority of the glioma patient specimens regardless of grade, but less abundant than CD4+ T lymphocytes." (PMID 35269652, 2022). "Using a preclinical glioma model, we demonstrate that CCR2+/CX3CR1+ cells are sourced from the bone marrow, suppress both CD4+ and CD8+ T cells, migrate to CCL2 and/or CCL7 in a CCR2-dependent manner, and are reduced in the glioma microenvironment through combination targeting of CCL2 and CCL7." (PMID 36685592, 2022). "Taken together, these results indicate that reduced astrocytic Cxcl10 expression in glioma-bearing mouse strains likely reflects an absence of CD4 T cells, which induce Cxcl10 expression in astrocytes to hinder LGG growth in vivo." (PMID 35986378, 2022). "Moreover, NCAPG expression was positively correlated with immune cell infiltration into gliomas in general and with the infiltration of B cells, CD4+ T cells, CD8+ T cells, macrophages, neutrophils, and dendritic cells in glioma." (PMID 35280743, 2022). "It suggests that SDC1 may have a positive correlation with activated CD4+T and CD8+T cells in the TME of glioma." (PMID 35669186, 2022). "Moreover, SLC1A5 expression correlated positively with the numbers of tumor-infiltrating B cells, CD4+ T and CD8+ T cells, macrophages, neutrophils, and dendritic cells in HCC and in lower-grade glioma (LGG)." (PMID 34367941, 2021). "Single-cell sequencing data showed that CREM is highly expressed in the CD4+ CTLA4 and CD8+ LAYN population in non-small cell lung cancer, and CREM is highly expressed in the CD8+ T-cell exhaustion population in glioma." (PMID 34938728, 2021). "The percentage of CD4+ T helper cells in grade IV glioma patients at first diagnosis, but not that of CD3+/CD8+ cytotoxic T cells, was significantly lower than in healthy controls (ANOVA, post-hoc Tukey test, *p < 0.05)." (PMID 34079819, 2021). "Studies showed that the number of CD4+ T cells, CD8+ T cells, and Treg cells could affect the tumor immune response in gliomas." (PMID 35096561, 2021). "Importantly, EVA1B overexpression was associated with the immune infiltration levels of immune cells including B cells, CD4+ T cells, CD8+ T cells, macrophages, and neutrophils, and strongly with the overall immune infiltration levels of glioma." (PMID 33889156, 2021).
glioma (continued). "After adjusting for the influence of glioma purity, we found that high expression of B2M in LGGs was correlated with high levels of infiltration of B cells, CD8+ T cells, CD4+ T cells, macrophages, NK cells, and dendritic cells, while low expression of B2M yielded opposite results." (PMID 33960680, 2021). "In this study, IRF expression was correlated with infiltration of the six immune cell types in glioma, including B cells, CD8+, CD4+ T cells, macrophages, and dendritic cells, and infiltration of some of these cells was independently associated with patient outcome." (PMID 33902005, 2021). "However, glioma microenvironment infiltrating CD8 and CD4 cells would exhibit limited effector functions, owing to the higher expression level of the immuno-suppressive molecule, IgSF11, in addition to other immune checkpoints." (PMID 33604291, 2020). "By eliciting a CD4+ T-cell response and generating memory T-cells selectively responsive to tumor antigen, ZIKV-based immunotherapy offers a promising avenue for providing long-term protection against glioma." (PMID 33002018, 2020). "The amount of intratumoral CD8+ and CD4+ T-cells per mm2 increased significantly in all treated groups in the GL261 glioma model (CD8+/mm2: CED-TMZ + GL261 vs. non-treated: p = 0.0022; CED-TMZ vs. non-treated: p = 0.0273; GL261 vs. non-treated: p = 0.022." (PMID 31900109, 2020). "In human beings, CD4+ and CD8+ cytotoxic T lymphocytes are well-suited for the destruction of glioma cells due to their ability to recognize specific tumor antigens on the cell surface and have been shown to correlate with tumor inhibition and tumor regression." (PMID 31380398, 2019). "In absence of Tregs, CD8+ T cells from glioma patients are able to restore their proliferative and cytotoxic activities, while CD4+ T cells were able to expand in response to antigen stimulation." (PMID 30619286, 2018). "The critical roles of CTLA-4 in regulating immunosuppressive antitumor responses have been illustrated in glioma, which suggest that anti-CTLA-4 treatment will largely enhance CD4+ T-cell proliferation and restore the Treg/CD4+ ratio to further support the antitumor response." (PMID 30619286, 2018). "As shown by flow cytometry assay, the glioma-specific Th9 cells, but not the naïve CD4+ T cells, markedly induced GL261 cell apoptosis; the apoptosis was abolished by the presence of anti-IL-9 antibody." (PMID 28002799, 2017). "Treating CD4+ CD25− T cells with both SEB and glioma Ag induced glioma-specific Th9 cells." (PMID 28002799, 2017). "The tumor cells are no longer shielded from host immune system, and consequently, the proinflammatory Th1 cytokines, such as IFNγ, may recruit adaptive CD4+ and CD8+ lymphocytes to the tumor site to instigate an anti-glioma immunity." (PMID 24827739, 2014). "In the SMA-560 mouse model of glioma, neutralization of CTLA-4 with monoclonal antibody, 9H10, confers a long-term survival benefit in 80% of treated mice with re-establishment of normal CD4 counts concomitant with a decreased Treg fraction." (PMID 23720663, 2013). "Subsequent observations found that thymus-derived nTreg, rather than glioma-induced iTreg, represent the predominant population of CD4+FoxP3+ T cells within brain tumors." (PMID 23720663, 2013). "However in our study, CD4+ CAR-T cells did not secrete enhanced levels of IL-2 upon exposure to glioma cells and failed to improve the therapeutic efficacy of CAR-NK cells." (PMID 40376677, 2025). "In addition, they and a more recent report from Fu and colleagues both showed that tumor-infiltrating CD4+ and CD8+ T cells expressed a significantly greater percentage of TIM-3 positivity compared to peripheral CD4+ and CD8+ T cells in matched glioma and glioblastoma samples respectively." (PMID 40072074, 2025).